CLDN5 (claudin 5)
Diseases named in the same sentence as CLDN5 in open-access papers (continued):
Sharing a sentence is not in itself a finding about the gene and the disease.
liver cancer (1 paper, 2025). An epithelial or non-epithelial malignant neoplasm that arises from the liver. "Furthermore, to investigate the correlation of CD34+CLDN5+ ECs with overall survival duration in primary liver cancer patients, mIHC were performed on tissue microarrays containing 66 primary liver cancer specimens with long-term clinical follow-up data." (PMID 39674501, 2025). "Within our project, sc-RNA seq analysis was employed to explore the heterogeneity of ECs throughout the initiation and progression of primary liver cancer, and identified a unique subset of tumor associated senescent CD34+CLDN5+ECs, which were mainly present in the tumor tissue." (PMID 39674501, 2025). "The CD34+CLDN5+ cells with senescent features not only predominantly exited in iCCA and cHCC-CCA patients, but also were related with the patients' survival duration of liver cancer." (PMID 39674501, 2025).
liver disease (1 paper, 2012). "Thus the differences in claudin-5 expression between LSECs of healthy young rats and human livers may be due to the fact that the human liver samples available for investigation were derived from older patients that had succumbed to liver disease." (PMID 22509281, 2012).
lymphedema (1 paper, 2023). Excess fluid collection in tissues, causing swelling. "Genes associated with lymphangiogenesis and the junctional paracellular permeability of vessels such as GJA1, CLDN5 and VEGFR3 were found upregulated only in secondary lymphedema, where true edema is present." (PMID 37108757, 2023).
lymphoma (1 paper, 2019). A malignant (clonal) proliferation of B- lymphocytes or T- lymphocytes which involves the lymph nodes, bone marrow and/or extranodal sites. "A gene involved in formation of tight junctions showed inherent upregulation in resistant line 61 BMDMs (CLDN5), whereas CD72, which is involved in lymphoma of the small intestine, was highly expressed in MD-susceptible chickens." (PMID 30678299, 2019).
major depressive episode (1 paper, 2023). "Furthermore, TNF-α could affect blood–brain barrier permeability and CLDN5 expression of endothelial cells in major depressive episodes." (PMID 38111702, 2023).
malaria (1 paper, 2012). Malaria is a serious and sometimes fatal disease caused by a parasite that commonly infects a certain type of mosquito which feeds on humans. "Similarly, degradation of claudin-5 was associated with an increase in dermal microvascular permeability in an in vitro model of malaria and knockdown of claudin-5 in human umbilical vein endothelium caused a decrease in endothelial monolayer electrical resistance." (PMID 23115643, 2012).
meningioma (1 paper, 2017). A generally slow growing tumor attached to the dura mater. "In this study, for the first time, we have evaluated the expression of Dkk-3 and claudin-5 in a series of meningiomas." (PMID 28978116, 2017). "The aim of our study is to demonstrate the role of Dkk-3 and claudin-5 in the pathogenesis of meningiomas." (PMID 28978116, 2017). "At western blot analysis, the data have shown a significantly reduction of Dkk-3 and claudin-5 expression in the meningioma tissue compared with control tissues." (PMID 28978116, 2017). "Our findings suggest that Dkk-3 and claudin-5 could be considered as potential targets for therapeutic approaches in the treatment of meningiomas." (PMID 28978116, 2017). "ID score for claudin-5 was 2 in 8, 3 in 4 and 4 in 1 grade I meningiomas." (PMID 28978116, 2017). "Interestingly, in a similar manner, also the values of claudin-5 are poorly expressed in both sets of meningiomas." (PMID 28978116, 2017). "The purpose of this study was to evaluate the expression of Dkk-3 and claudin-5 in a series of 30 WHO grade I and grade II meningiomas." (PMID 28978116, 2017). "Nowadays, no study has evaluated the expression of Dkk-3 and claudin-5 in meningiomas." (PMID 28978116, 2017).
metabolic syndrome (1 paper, 2023). A cluster of metabolic risk factors for CARDIOVASCULAR DISEASES and TYPE 2 DIABETES MELLITUS. "In addition, Per2 (a transcriptional repressor of circadian rhythm) mutant mice do not show any metabolic syndromes, but show significant attenuation of CLDN5 expression and an increase in retinal permeability." (PMID 37095509, 2023).
MPS III A (1 paper, 2013). "Although lessened expression of claudin-5 was established in all analyzed brain structures in MPS III A patient, a more pronounced decline in expression of this protein was determined in hippocampus and cerebellum from MPS III D patient." (PMID 24225396, 2013).
MPS III D (1 paper, 2013). "In brain tissues from the MPS III D patient, a major decrease of occludin expression was seen only in primary motor cortex and claudin-5 – in hippocampus and cerebellum." (PMID 24225396, 2013).
Nephropathy (1 paper, 2022). A nonspecific term referring to disease or damage of the kidneys. "Crucially, in two DN models, animals with a podocyte-specific deletion of CLDN5 exhibited a more severe nephropathy, including more proteinuria, and evidence of more marked podocyte injury, but interestingly also more severe interstitial fibrosis." (PMID 35332151, 2022).
nephrosis (1 paper, 2014). Pathological processes of the KIDNEY without inflammatory or neoplastic components. "Claudin-5 can be found at the apical membrane of the rat podocytes of puromycin aminonucleoside (PAN) induced nephrosis, and claudin-1 can be found in basolateral membrane of rat epididymis." (PMID 24868462, 2014).
neuropathy (1 paper, 2021). A disorder affecting the nervous system that manifests with pain, tingling, numbness, and/or muscle weakness. "A decrease in claudin-5 allows for capillary leakage in neuropathy." (PMID 34576252, 2021).
Norrie disease (1 paper, 2024). A rare X-linked genetic vitreoretinal condition characterized by abnormal retinal development with congenital blindness. "These included the vascular endothelial tight junction gene Cldn5 and endothelial transporters Abcb1a, Slc7a1, Slc7a5, and Plvap, emphasizing the involvement of the cochlear vascular barrier in Norrie disease." (PMID 39585982, 2024).
pancreatic ductal adenocarcinoma (1 paper, 2020). An infiltrating adenocarcinoma that arises from the epithelial cells of the pancreas. "Interestingly, CLDN5 was also found to be aberrantly methylated in pancreatic ductal adenocarcinomas." (PMID 32156068, 2020).
pancreatic endocrine tumor (1 paper, 2023). "Claudin-5 is significantly positively expressed in pancreatic solid-pseudopapillary tumor cell membranes (SPN), but not in pancreatic neuroendocrine tumors (P-NET), and combined IHC detection of claudin-5 and intercellular adhesion molecule, CD99, is required for the diagnosis of SPN and P-NET." (PMID 36959784, 2023). "Furthermore, SPT is positive for claudin-18.2and claudin-7 in a few cases, and pancreatic endocrine tumor (PET), acinar cell carcinoma(ACC), and pancreatoblastoma (PB) show strong expression of claudin-7 and a lack of claudin-5 expression." (PMID 36959784, 2023).
pancreatitis (1 paper, 2011). Inflammation of the pancreas. "Similar results come from experimentally induced pancreatitis in rats where the mRNA levels of claudin 4, claudin 5 and occludin decreased due to pancreatitis induced lung injury but increased after administration of emodin, a chemical suggested to enhance epithelial barrier function." (PMID 21619599, 2011).
panic disorder (1 paper, 2025). An anxiety disorder characterized by multiple unexpected panic attacks with persistent concern of recurring attacks. "Claudin-5 levels (p = 0.001) and Panic Disorder Scale (PDS) scores (p < 0.001) of the PD group decreased significantly after 6 weeks of follow-up compared to those at baseline." (PMID 41458033, 2025).
periodontal disease (1 paper, 2023). "The increase in serum IL-6 due to periodontal disease reduced claudin-5 levels in the brain blood vessels, resulting in increased BBB permeability." (PMID 37440496, 2023).
periodontitis (1 paper, 2026). An acute or chronic inflammatory process that affects the tissues that surround and support the teeth. "gingivalis successfully induced periodontitis in mice and led to EndoMT in the hippocampus, characterized by downregulation of ZO-1 and Claudin-5 and upregulation of α-SMA, along with inflammatory activation evidenced by elevated levels of iNOS, IL-1β mRNA, and IL-6 mRNA." (PMID 41908490, 2026).
retinal diseases (1 paper, 2025). "Indeed, decreased CLDN-5 expression has now been observed across many neurological and retinal diseases." (PMID 41361961, 2025).
Salmonella Infections (1 paper, 2018). Infections with bacteria of the genus SALMONELLA. "In comparison with the NC group, Salmonella infection (the SAL group) significantly decreased mRNA levels of ZO-1 and CLDN-5 and increased the mRNA level of CLDN-2 (P < 0.05)." (PMID 29396554, 2018). "The down-regulation of ZO-1 and CLDN-5 and the up-regulation of CLDN-2 due to Salmonella infection were eliminated in the LAC + SAL group." (PMID 29396554, 2018).
sarcoma (1 paper, 2021). A usually aggressive malignant neoplasm of the soft tissue or bone. "Claudin-5 could be used as a marker with greater sensitivity and could also be of diagnostic value in the differential diagnosis of canine HSAs from other sarcomas with hemorrhage or increased vascularization." (PMID 34438863, 2021).
serous carcinoma (1 paper, 2023). "Expression of claudin-5 was associated with high grade, advanced stage and poor overall and disease-specific survival in analysis of ovarian specimens of serous carcinoma." (PMID 37067588, 2023).
status epilepticus (1 paper, 2022). Status epilepticus is defined as a continuous seizure lasting more than 30 min, or two or more seizures without full recovery of consciousness between any of them. "Following kainic acid injection, Cldn5 heterozygous mice had shorter latency to seizure onset, while 100% (5/5) of heterozygous mice entered status epilepticus, defined as more than 5 min of continuous seizures, compared to 16% (1/6) of WT mice." (PMID 35422069, 2022).
systemic lupus erythematosus (1 paper, 2024). An autoimmune multi-organ disease typically associated with vasculopathy and autoantibody production. "Recent evidence of microglial expression of the TJ protein, claudin-5, at the vasculature was observed in a systemic lupus erythematosus (SLE) mouse model." (PMID 38550920, 2024).
testicular germ cell tumor (1 paper, 2023). A germ cell tumor arising from the testis. "In particular, CD8+ T cell infiltration was also positively correlated with high CLDN5 expression in BLCA, BRCA, KIRP, brain LGG, LIHC, PAAD, PCPG, PRAD, READ, testicular germ cell tumor (TGCT), thymoma (THYM), UCEC, and UVM (P<0.05)." (PMID 37286335, 2023).
transient cerebral ischemia (1 paper, 2015). "Furthermore, linagliptin significantly increased cerebral claudin-5 and significantly decreased gp91phox in diabetic mice subjected to transient cerebral ischemia." (PMID 25986579, 2015).
type 1 diabetic (1 paper, 2022). "Metalloproteinase-2 and -9 (MMP-2/9), whose activities are known to be increased in the plasma of type 1 diabetic patients, have the potential for claudin-5 degradation, while caveolae-mediated internalization of claudin-5 can be promoted by the pro-inflammatory cytokine CCL-249." (PMID 35264685, 2022).
ulcer (1 paper, 2025). "Furthermore, CRPs upregulate TJs proteins expression (occludin, ZO-1, Claudin-5) to restore both the structural and functional integrity of the gastric mucosal barrier, consequently preventing ulcer progression." (PMID 40647169, 2025).
Ureteral obstruction (1 paper, 2022). Obstruction of the flow of urine through the ureter. "Podocyte-derived WIF1 also plays paracrine roles in tubular epithelial cells, as evidenced by the finding that animals with podocyte-specific deletion of Cldn5 or Wif1 have worse kidney fibrosis after unilateral ureteral obstruction than littermate controls." (PMID 35332151, 2022).
uveal melanoma (1 paper, 2023). A melanoma derived from melanocytes of the uveal tract. "Based on the Cox regression analysis of 33 cancers, in seven cancers, including STAD, uveal melanoma (UVM), KIRP, COAD, THCA, UCEC, and PAAD, CLDN5 expression was significantly correlated with OS." (PMID 37286335, 2023).
tumor (94 papers, 2005 to 2026). "Using single-cell RNA sequencing, we identified a distinct senescent-associated subset of endothelial cells (ECs), namely CD34+CLDN5+ ECs, which mainly enriched in tumor tissue." (PMID 39674501, 2025). "Elevated ADAR1 levels are associated with stromal markers such as CLDN5 in the tumor microenvironment (TME)." (PMID 40852728, 2025). "Across different cancer types, the focus has been on the potential connection between the expression of CLDN5, immune infiltration, tumor mutational burden (TMB), microsatellite instability (MSI), and diverse immune-related effects." (PMID 37286335, 2023). "The result suggests that CLDN5 was negatively associated with a majority of methylesterases in several tumor species, indicating that methylesterases (specifically m6A methylesterases) regulate CLDN5 transcription." (PMID 37286335, 2023). "We determined that CLDN5 was associated with the prognosis of most tumours by difference-in-difference and survival analyses." (PMID 37286335, 2023). "CLDN5 appears to be linked to tumor metastasis and tumor immunotherapy, but further studies are required to confirm this." (PMID 37286335, 2023). "Research has indicated that CLDN5 is associated with tumor metastasis, the tumor microenvironment, and immunotherapy in multiple types of cancer." (PMID 37286335, 2023). "As TMB level is commonly regarded as a remarkable biomarker associated with treatment effects in many immune checkpoint inhibitor (ICI)–treated tumors, CLDN5 mutation predicts the therapeutic efficacy of ICIs across tumor types." (PMID 37286335, 2023). "In this study, we demonstrated that TLR-4 gene deficiency preserved Dkk-3 and claudin-5 expressions and promoted apoptosis process, so determining a slowing of tumor growth." (PMID 30680070, 2018). "In addition to mediating vascular permeability, Cldn5 has been implicated in cell motility and proliferation of endothelial and tumor cells." (PMID 38190417, 2024). "We speculated that the reduction of CLDN5 may downregulate hedgehog signaling pathway, which causes endothelial barrier breakdown and increases the aggressiveness of tumor." (PMID 38186223, 2024). "We also identified an association between Claudin-5 expression and tumor stage." (PMID 34438863, 2021). "The altered expression of claudin-5, probably related to the overproduction of cytokines of tumor cells, could cause an alteration of the adjustment of the BBB with an increase of the permeability favoring, thus, cell migration and edema formation." (PMID 28978116, 2017). "However, in tumor models of endothelial cells and mice, Angptl4 caused endothelial barrier damage by integrin signaling and disruption of intercellular VE-cadherin and claudin-5 clusters." (PMID 29912977, 2018). "Subsequent histological examination (H&E) and mIHC of tumor lesions revealed that CD34+CLDN5+ ECs significantly contributed to the development of CCA within HCC." (PMID 39674501, 2025). "The several tasks that CLDN5 plays in tumor growth, metastasis, and the TME have drawn attention to it in the cancer setting." (PMID 40852728, 2025). "The results demonstrated that the IGF2 mainly expressed at CD34+CLDN5+ double positive cells in tumor tissue." (PMID 39674501, 2025). "Overall, our study suggests that Rab27 proteins control tight junctional apparatus of the brain microvasculature, including claudin 5, and that disruption of this mechanism enables marked influx of immune cells into the tumor microenvironment." (PMID 40408475, 2025). "Claudin-5 positivity is observed in both vasoformative and solid areas of the tumor, with most cases showing positivity in more than 50% of tumor cells, often approaching 100%." (PMID 40666093, 2025). "NIR-OND was nearly exclusive to claudin-5-positive areas in both tumour and non-tumour regions, suggesting that free NIR-OND was restricted to the vasculature." (PMID 39984637, 2025).